TNF (tumor necrosis factor)
Diseases named in the same sentence as TNF in open-access papers (continued):
Sharing a sentence is not in itself a finding about the gene and the disease.
tumor (continued). "Als kompatibel mit einer Schwangerschaft gelten die Antirheumatika Hydroxychloroquin, Sulfasalazin, Azathioprin, Ciclosporin, Tacrolimus, Colchicum, nichtselektive NSAR (nichtsteroidale Antirheumatika), niedrig dosiertes Prednison/Prednisolon sowie TNF(Tumor-Nekrose-Faktor)-Hemmer." (PMID 34581874, 2021). "However, iso1Au/IL12 can also induce the release of sTNF-R2 in the tumor microenvironment, an inhibitor of TNF." (PMID 33952242, 2021). "The cytokine levels also did not change in response to the decrease in FAP+ cells, which supports the latter hypothesis that FAP reduces the response of tumor cells to tumor necrosis factor alpha and IFNγ." (PMID 34490078, 2021). "Similarly, disruption of Ezh2 activity or depletion of Helios in Tregs leads to Foxp3 instability with an increased expression of effector cytokines like IFNγ and TNFα, enhanced anti-tumor immunity, and decreased tumor growth and progression." (PMID 34394124, 2021). "Furthermore, parvoviruses were engineered as vehicles of IFN-γ inducible protein 10 (CXCL10) and TNF-α, showing a synergic effect in tumor regression in rats HGGs models." (PMID 34439595, 2021). "Thus, in this study we exposed TNBC cells to a persistent stimulation by TNFα + IL-1β together and determined the effects of this stimulatory setup on tumor cell phenotypes and activities." (PMID 34072893, 2021). "TNF-α is a cytokine produced by macrophages, with a role in the inflammatory response, cellular immunity, tumor immunity, and other physiological processes, while IL-6 is a pro-inflammatory cytokine that stimulates the immune system to repair damaged cells and promote the host survival." (PMID 33919822, 2021). "We analysed differentially expressed mRNA transcripts in tumor of WT mice in comparison to KO tumor and detected an average >2-fold increase in the myc gene family, anti-apoptotic genes and tumor necrosis factors (TNF)." (PMID 34685767, 2021). "F8-TNF is an antibody fusion protein which delivers TNF to the tumor extracellular matrix." (PMID 34631734, 2021). "NK/DC signaling can occur via Flt3L, IFNγ and TNFα and may be a crucial factor in augmenting cross-priming and anti-tumor responses." (PMID 34552594, 2021). "Interestingly, rejection of CEA-negative tumours was macrophage and TNF-α dependent, suggesting that IL-12 release inside the tumour recruits and stimulates macrophages with an anti-tumour phenotype." (PMID 34885108, 2021). "Moreover, several pro-inflammatory cytokines, including TNF-α, IL-1β, IL-6 and IL-17, and induced cell apoptosis are decreased with anti-TNF-α treatment in HCC tumor cells." (PMID 34948424, 2021). "As a result, HDIs may aid tumour therapy by reducing tumour cell responsiveness to TNF-mediated NF-B pathway activation." (PMID 34820248, 2021). "Moreover, the concentrations of TNF‐α were closely significant correlated with the levels of CD54+ neutrophils or B7‐H2+ neutrophils in tumor tissues." (PMID 34185422, 2021). "On a biological level, increased GP88 expression may have beneficial anti-inflammatory effects because it targets tumor necrosis factor receptors (TNFRs), thereby diminishing TNFα action and resulting in decreased tumor aggressiveness." (PMID 34064411, 2021). "Despite TNF’s anti-tumour actions, TNF is involved in a range of inflammatory and pro-tumour pathways which may lead to poor prognosis in GC." (PMID 34944729, 2021). "Besides direct transcribing cell proliferation‐related genes, NF‐κB also induces the expression of proinflammatory cytokines such as IL‐1β, IL‐6, and TNFα, which play a key role in the NF‐κB‐dependent tumor cell proliferation." (PMID 34977871, 2021). "As the name implies, TNF is an extremely potent cytokine that can induce tumor necrosis." (PMID 34771644, 2021). "Furthermore, in vitro co-culture models have shown that tumor cell-macrophage co-culture induced M2-like polarization via increased expression of IL-10, IL-12, IL-6, TNF-α, CCL5, CCL22, and CSF1." (PMID 34439281, 2021).
tumor (continued). "Indeed, preclinical studies on murine models of brain metastases have shown that systemic administration of TNF can permeabilize the BBTB to the anti-human epidermal growth factor receptor (HER) 2 mAb trastuzumab at tumor sites." (PMID 34063335, 2021). "Since TGF-β represents an immunosuppressive effect and IL-10 is an iconic inflammatory factor of M2 macrophages 14, we speculated that TNF-α might be an important anti-tumor inflammatory factor in RIAE." (PMID 33867819, 2021). "Furthermore, we pre-selected tumor type and concentrations of Granzyme-B, TNFα, and IFN-γ on day seven for evaluation on model parameter Vmax5,2." (PMID 34205020, 2021). "Indeed, tumor cell proliferation and migration stimulate inflammatory cytokine production, including IL-6, IL-8, and TNF-α." (PMID 33550763, 2021). "Besides, growth and differentiation factor 15 (GDF-15), a direct target of nuclear factor kappa B (NF-κB) in tumor cells, suppresses the pro-apoptotic activity of macrophages by inhibiting tumor necrosis factor (TNF) and nitric oxide (NO) production." (PMID 34290984, 2021). "Moreover, in most patient tumors TNFα and IL-1β were concomitantly expressed at the tumor site and in patient materials." (PMID 34072893, 2021). "Various strategies of CRISPR screen for novel immunotherapy (IO) targets discovery have been used, including targeting antigen processing and presentation, IFN-γ pathway, TNF signaling, epigenetic regulators, and PD-L1 regulators in tumor cells, and metabolic regulators in T cells." (PMID 34095145, 2021). "In addition, the TNF-α secretion was quantified, which promotes B cell differentiation, activates NK cells, and helps in the selective killing of tumor cells." (PMID 34373697, 2021). "While the classical form of neutrophils, called N1 TANs, can effectively eliminate tumor cells via lysis, TNF-α, or inducing tumor cell apoptosis, another form, called N2 TANs, can support tumor growth, invasion, metastasis and ultimately, poor clinical outcomes in many cancers." (PMID 33596197, 2021). "Tumour‐induced increased TNFα secretion by macrophages could further promote PI3Kα‐driven tumour cell migration." (PMID 34033220, 2021). "In cancer cachexia, both tumor cells and tumor-activating immune cells express proinflammatory cytokines, including tumor necrosis factor (TNF)-α, interleukin (IL)-1, IL-6, IL-8, and interferon (IFN)γ, all of which systemically affect various organs such as the brain, liver, muscle, and fat." (PMID 33801569, 2021). "Then, 24 h later, TNF-α production and tumor cell lysis were analyzed." (PMID 33776765, 2021). "We next explored whether TNFα influences the expression of two key regulators of anti-tumor immunity, PD-L1 and PD-L2." (PMID 34073253, 2021). "Delivery of high-dose TNF locally into tumors can induce massive necroptosis and tumor regression." (PMID 34771644, 2021). "DOX administration reduced tumor-induced upregulation of IL-1β and TNF-α." (PMID 34445729, 2021). "Indeed, the activation of the NKG2D pathway induces the secretion of cytotoxic granules, interferon-γ (IFN-γ) and tumor necrosis factor-α (TNF-α), finally promoting the cytotoxicity of γδ-T cells against infected cells or tumor cells." (PMID 33777016, 2021). "In addition, Tien-Hsien liquid (THL) accelerated the secretion of immune factors including IFN-γ, IL-2 and TNF-α to augment the cytotoxicity of NK cells and CTLs and mitigate the tumor development." (PMID 34722304, 2021). "Similarly, TNFα coded by an NF‐κB target gene TNFA acts as a strong activator of NF‐κB, functions in many tumor cells with constitutive activation of NF‐κB in an autocrine manner (usually stromal)." (PMID 34977871, 2021). "We then asked whether Gal-9 expression is regulated by immunomodulatory cytokines/factors that are typically present in the TME during an anti-tumor immune response, including IFNβ, IFNγ, and TNFα." (PMID 33547304, 2021).
tumor (continued). "Indeed, in vitro, CD4+ CAR T cells were shown to exert cytotoxic activity against tumor cells, although at a lower level than CD8+ CAR T cells, but to produce more IFN-γ and TNF, and to proliferate more extensively upon contact with tumor cells." (PMID 33546283, 2021). "Epithelia cells in tumor show a lower activation of tumor necrosis factor signaling from B cells." (PMID 33463049, 2021). "M1 macrophages are stimulated by IFN-γ, LPS, TNF-α or GM-CSF, and inhibit tumor growth by producing pro-inflammatory cytokines such as: IL-1, -6, -8, -12, -23, TNF-α, small quantities of IL-10 as well as ROS (reactive oxygen species) and RNI (reactive nitrogen intermediates)." (PMID 33146401, 2021). "Accumulating evidence shows that TNF-α contributes to tumor initiation and progression." (PMID 33925516, 2021). "Lastly, TNF is a product of both activated macrophages and the cells of the TME; in addition to being an anti-cancer cytokine, it has been implicated in the inflammatory process necessary for tumor growth." (PMID 34122412, 2021). "In our study, TPH104 increased the expression of TNF-α mRNA, particularly in transformed cells, which could increase the immune response to the tumor in the TME." (PMID 33919653, 2021). "However, the remarkable exception to this tumor-associated suppression was the MAC-MT subset, which showed a significant increase in the expression in IFNγ-, TNF-, and fatty acid–stimulated macrophage gene signatures." (PMID 34936871, 2021). "The activation of the caspase-8-GSDMC pathway by TNF-α derived from macrophages may account at least in part for tumor necrosis in hypoxic regions, as blocking this signaling pathway drastically reduced areas of necrosis in cancer xenografts in vivo." (PMID 33406603, 2021). "In tumorigenesis for example, NF-κB regulates pro-inflammatory genes such as cytokines and chemokines (e.g., TNF, IL-1, IL-6, IL-8, IL-17), proliferative (cyclin D1, Cyclin E) and anti-apoptotic genes (Bcl-2, Bcl-xL), which can enhance tumor growth and survival." (PMID 34572737, 2021). "Hence, TNFα proved to be both a dose-limiting factor as well as crucial for the anti-tumor immune stimulatory capacity of Ad.IFNβ." (PMID 34445397, 2021). "TNFα in the cGAMP-treated LLC tumours was reduced by 81% in STINGΔMC mice compared with WT mice." (PMID 34285232, 2021). "Inflammatory cytokines, such as TNF-α, IL-1β, and IL-6, are also found in tumor biopsy samples." (PMID 34194957, 2021). "The mechanism could be due to TNF/TNFR1/TNFR2 signals promoting tumor growth, evading immune attacks, or triggering adverse effects in patients." (PMID 33373873, 2021). "As tumor-bearing organisms are usually in a state of immunosuppression, the promotion of the secretion of IP-10 and TNF-α may activate the immune response and exhibit antitumor effect." (PMID 33841142, 2021). "Importantly, we found that virus that had transduced tumor was functional and able to express its transgenes IL-2 and TNF-a." (PMID 32920593, 2021). "M2-like macrophages have been reported to upregulate the expression of the glucose-regulated protein of 78 kDa (GRP78) in tumor cells, promoting STAT3 phosphorylation, leading to the downstream inflammatory factors including IL-1β and TNF-α upregulation, which facilitates tumor progression." (PMID 34326840, 2021). "Besides, administration of Salmonella also recruits macrophages into tumor tissue, which then secrete TNF-α and IL-1β for exerting anticancer effects." (PMID 33717106, 2021). "On the one hand, high levels of cytotoxic potential from TNF-α could render destruction of tumor vasculature, necrosis and apoptosis of cancer cells, and facilitation of drug accumulation inside tumor sites." (PMID 34497832, 2021). "TGF-β, IL-6, and TNF-α play a role in tumor formation in conditions of chronic inflammation." (PMID 33567693, 2021).
tumor (continued). "The authors suggested that this impaired secretion of TNF-α and IL-12 by peripheral mDCs may diminish T cell-mediated anti-tumor immunity, though this too warrants additional investigation." (PMID 34067257, 2021). "The BO-treatment significantly inhibited the mRNA expression of IL-6 and TNF-α in tumor tissues." (PMID 34869511, 2021). "Reimplantation of Alistipes shahii into MC38 tumor-bearing mice could rescue TNF level and enhance immunotherapeutic effects." (PMID 35096962, 2021). "This study investigated the effects of TNF-α stimulate on ADSCs in the tumor microenvironment." (PMID 33924332, 2021). "The gene expression of multiple inflammatory markers in the heart was significantly upregulated in tumor-bearing mice as compared to tumor-free mice, including the pro-inflammatory cytokines IL-1α, IL-1β, IL-6, and TNF- α and the inflammatory chemokines Mcp-1, Cxcl1, and Cxcl10." (PMID 34445729, 2021). "Notably, our results show that markedly lower doses of iso1Au/TNF (equivalent to 5–10 pg of bioactive TNF) are sufficient to affect vascular permeability, tumor perfusion and antitumor efficacy of chemotherapy." (PMID 33952242, 2021). "Generally, chemotherapy or environmental stresses like hypoxia can promote TAMs to overexpress IL-8 and its receptors, while tumor cells could also be stimulated to secrete IL-8 after NF-κB is activated by TNF-α and IL-1α." (PMID 34625124, 2021). "Accordingly, when TNBC cells were continuously stimulated by TNFα + IL-1β, their ability to secrete factors that induce the recruitment of monocytes and neutrophils to matrigel plugs in vivo was reduced by treating the tumor cells with a glycolysis inhibitor." (PMID 34072893, 2021). "Tumor suppressive EMT-related hsa-miR-145 promotes TNF-α-induced apoptosis through targeting cIAP1and may serve as a potential biomarker for an early diagnosis of TNBC." (PMID 33664322, 2021). "In this study they found that this combination therapy concurrently decreased tumour growth whilst significantly increasing proinflammatory TNFα, IFNγ and MCP-1 cytokine and chemokine expression, concomitant with a significant reduction in the M2-polarised macrophage population." (PMID 34944870, 2021). "Studies have emphasized the essential role of TNF-α in tumour growth and angiogenesis in MM." (PMID 33808304, 2021). "Similarly to TGFβ, the role played by TNFα in cancer progression is both tumor-inhibiting and tumor-promoting, depending on the cell context and the cancer stage." (PMID 34360868, 2021). "In contrast, other studies indicated that inflammation up‐regulated nitrite and TNF‐α activating caspase‐3 induced apoptosis in the tumour cells, and enhanced antitumour T cell immunity by decreasing immunosuppressive infiltration of myeloid‐derived suppressor cells and Treg cells." (PMID 33410581, 2021). "Increased TNFα in tumor microenvironment was responsible for more metastasis." (PMID 34182543, 2021). "Since MMP3 is known to be involved in tumor cell invasion, we investigated whether TNFα induces FDCLC migration and whether MMP3 expression is required for this." (PMID 34222497, 2021). "The classically activated microglia/macrophages stimulate anti-tumor immune responses through the secretion of pro-inflammatory cytokines, such as tumor necrosis factor-alpha (TNF-α), interleukin (IL)-1β, and inducible nitric oxide synthase, defined as M1 markers." (PMID 34267749, 2021). "On the other hand, studies also showed that TNF-α secreted by host cells surrounding tumor tissues could instead construct an inflammatory status and promote tumor progression." (PMID 34497832, 2021). "A novel subpopulation of CD3-CD4+ cells with high TNFα and Foxp3 expression may modulate the tumor microenvironment and play a proinflammatory role." (PMID 33869005, 2021). "The potent anti-tumor activity with reduced toxicity may provide L19-TNFI97A a broader therapeutic index when compared to conventional immunocytokines based on wild type TNF." (PMID 34576184, 2021).
tumor (continued). "In a mouse model of breast cancer with tumor-bearing mice, knockout of biglycan in the stroma inhibited metastasis to the lung, impaired tumor angiogenesis and normalized tumor vasculature by repressing TNF-α and angiopoietin 2 (ANGPT2) signaling." (PMID 34917515, 2021). "Thus, TNF-α plays the role of an endogenous tumor promoter, and chemical tumor promoters are inducers of TNF-α in their target organs." (PMID 33804551, 2021). "Our results also show that IFNγ and TNFα have opposite effects in the tumor microenvironment." (PMID 34869307, 2021). "CSG targeting of TNFα is critical to induce vessel dilation and improve tumour perfusion." (PMID 34683956, 2021). "Similar to what we proposed for allograft survival, the level of pro– and anti–programmed cell death molecules within the tumor may determine response to immunotherapy that includes TNF-producing T cells." (PMID 34752416, 2021). "Moreover, TNF-α is mainly secreted by macrophages and plays an important role in the onset of inflammation, which and involved in the regulation of tumor microenvironment and the development in diseases." (PMID 33968087, 2021). "M1 macrophages could secrete high levels of proinflammatory cytokines such as TNF-α and low levels of IL-10, which facilitate a robust anti-tumor activity." (PMID 33867819, 2021). "Interestingly, tumor-inhibiting effect of TNF therapy in NC101-colonized mice was disappeared when the anti-TNF-treated mice were co-housed with PBS-treated mice in the DSS/Apcmin/+ mouse model." (PMID 33578830, 2021). "Though TNF-α is most known to induce apoptosis and regulate the inflammatory process to inhibit neoplasm cells, research shows that the presence of TNF-α in a tumor microenvironment might promote angiogenesis, migration, and cell invasion." (PMID 34573967, 2021). "Cytotoxicity to tumor cell lines was an early recorded activity of the cytokine TNF-α, formerly known as cachectin, that is produced by a variety of haemopoietic cells including monocytes, macrophages, T lymphocytes and B cells and, in the CNS, by glial cells and neurons." (PMID 33853634, 2021). "Overall, TNF-α appears a key player in tumor invasion and metastasis in ccRCC." (PMID 33920158, 2021). "We therefore hypothesized that ANGPT2 might be regulated by biglycan/TNF-α signaling, leading to the destabilization of tumor blood vessels." (PMID 33966638, 2021). "Regardless of the toxic effects of cancer patients caused by TNF-α treatment, MCPIP1 upregulation might help to kill tumor cells and reduce the amount of TNF-α treatment needed." (PMID 34356509, 2021). "Additionally, tumor weight was significantly decreased by combined treatment with tamoxifen and TNFα or sh-NCOR1 compared to single treatment with TNFα or sh-NCOR1 14 days after inoculation of tumor cells (p < 0.05)." (PMID 34073371, 2021). "In the present review, we describe recent advances in the development of novel soluble biomarkers (e.g., circulating immune cells, TMB, circulating tumor cells, circulating tumor DNA, soluble factor PD-L1, tumor necrosis factor, etc.)for patients with NSCLC treated with ICIs." (PMID 34503087, 2021). "Furthermore, tumor-derived TGFβ acts in synergy with TNFα to inhibit the ability of pDCs to produce IFNα via blocking IRF7 expression and nuclear translocation." (PMID 33919546, 2021). "Moreover, S. nigrum decreased blood serum TNF-α levels, which is consistent with the triggering of apoptosis in tumor cells." (PMID 33494738, 2021). "Its mutant form may activate TNFα and trigger a cascade of activation processes of other transcription factors, which leads to tumor transformation." (PMID 34885171, 2021). "The signal transducer and activator of transcription factor 3 (STAT3) signalling pathway is upregulated in TAMs and is responsible for the production of tumor-promoting inflammatory molecules, such as IL-10 and IL-6, as well as inhibition of the tumor-suppressive inflammatory molecule TNF." (PMID 33766119, 2021).